ERI2 (ERI1 exoribonuclease family member 2)
Synonyms: EXOD1; KIAA1504; MGC16943; ZGRF5
Tractability: Small molecule: a structure with a bound ligand is known. PROTAC: ubiquitination databases record sites on it.
Gene: Protein-coding gene on chromosome 16 (20,780,193 to 20,900,349, reverse strand). Ensembl gene ENSG00000196678.
Subcellular location (Human Protein Atlas): Nucleoplasm; Golgi apparatus
Gene Ontology:
Molecular function: 3'-5'-RNA exonuclease activity; nucleic acid binding; zinc ion binding
Biological process: exonucleolytic trimming to generate mature 3'-end of 5.8S rRNA from tricistronic rRNA transcript (SSU-rRNA, 5.8S rRNA, LSU-rRNA); negative regulation of regulatory ncRNA-mediated heterochromatin formation
Genetic constraint (gnomAD): Loss-of-function variants: 37 observed, 49.6 expected, observed/expected ratio (o/e) 0.75, 90% interval 0.57 to 0.98. The synonymous counts are far from expectation, so gnomAD's model fits this gene poorly and the ratio says little. Missense variants: 637 observed, 770.45 expected, observed/expected ratio (o/e) 0.83, 90% interval 0.77 to 0.88. Synonymous variants: 206 observed, 261.83 expected, observed/expected ratio (o/e) 0.79, 90% interval 0.7 to 0.88.
Homologues: Orthologues: macaque ERI2 (94% identical), chimpanzee ERI2 (86% identical), pig ERI2 (81% identical), dog ERI2 (80% identical), rabbit ERI2 (79% identical), guinea pig ERI2 (78% identical), rat Eri2 (75% identical), mouse Eri2 (75% identical), tropical clawed frog eri2 (45% identical), Drosophila melanogaster Snp (16% identical), zebrafish eri2 (15% identical). Paralogues in human: ERI1 (12% identical), ERI3 (12% identical).
Diseases named in the same sentence as ERI2 in open-access papers:
ERI2 is named in the same sentence as 6 diseases in open-access papers, as found by Europe PMC text mining. Sharing a sentence is not in itself a finding about the gene and the disease. The quoted sentences say what the papers report.
viral infection (2 papers, 2020 to 2021). "Similarly for ERI2, viral infection normally favors the shorter isoform, while inhibition of this isoform in favor of the longer version markedly inhibits viral infection and replication." (PMID 33269701, 2020). "Notably, we detect DIUs for several of the same genes (Setd5, Arhgap12, Gpbp1, and Eri2), suggesting that hnRNP K’s role in viral infection is conserved between mice and humans and may, in part, be mediated by the same alternative splicing events." (PMID 34305890, 2021).
left ventricular hypertrophy (1 paper, 2014). Enlargement of the LEFT VENTRICLE of the heart. "New discoveries include gene-based association of NSF with triglyceride levels and several genes (ACSM3, ERI2, IL18RAP, IL23RAP and NRG1) with left ventricular hypertrophy phenotypes." (PMID 25329069, 2014).
tumor (1 paper, 2022). "The Mann–Whitney U test was used to compare the mRNA expression relationship between MYC and INTS14 or ERI2 in a dataset featuring each tumor type." (PMID 35887071, 2022). "There was no dataset on tumor types with a significantly higher expression of MYC mRNA in the ERI2 mRNA high-expressing group." (PMID 35887071, 2022).
ERI2 also shares sentences with these, for which no sentence is quoted: breast carcinoma (1 paper); liver cancer (1); rhabdoid tumor (1).